CD4 (CD4 molecule)
Diseases named in the same sentence as CD4 in open-access papers (continued):
Sharing a sentence is not in itself a finding about the gene and the disease.
hematological malignancies (69 papers, 2011 to 2025). "DLBCL is marked by changes in T cell populations, notably demonstrating higher infiltration of CD8+ T cells relative to other hematologic malignancies, whereas the CD4+ T cell population is often considerably lower." (PMID 40599139, 2025). "It is common for patients with hematological malignancies and B cell impaired patients to experience prolonged virus shedding and to display an exhausted CD4+ T cell phenotype, leading to a dysfunctional T cell response overall during acute infection." (PMID 40431250, 2025). "Thereby, virus-specific CD4+ T cells were detectable in 81% of patients with solid tumors, compared to only 58% in those with hematological malignancies." (PMID 36839516, 2023). "Our results point out that in hematologic malignancies CD4+ and Tfh cells play the major role in the immune response to the SARS-CoV-2 vaccine." (PMID 37187728, 2023). "Types of immunosuppression were long‐term/high‐dose steroids or other immunosuppressant drugs (91.2%), active hematologic malignancy (4.4%), and active solid organ malignancy (4.4%), and the mean CD4 level was 213 cell/μL (150.3, 325.3)." (PMID 37634899, 2023). "In patients undergoing treatment for hematological malignancies, CD161+ CD4+ T cells have recently been linked to preserved immunity against CMV and lower risks for neutropenic infections." (PMID 29725326, 2018). "It has been reported that Th17 cells as a newly identified subset of CD4+ T cells are involved in the pathogenesis of several hematological disorders." (PMID 27176825, 2016). "The occurrence of PML in patients with hematologic malignancies with low CD4-cell counts has been reported before." (PMID 22747665, 2012). "Risk factors in human are advanced human immunodeficiency virus infection (CD4 T-lymphocyte count of 200 cells/mm3 or less), hematologic malignancies, and use of chronic corticosteroids and other immunosuppressive agents." (PMID 23320238, 2012). "Studies in other hematologic malignancies identified CD4/CD8 double-negative CAR T associated with enhanced CAR T persistence." (PMID 40610432, 2025). "In patients with hematological disorders receiving aHSCT, a low BC count is observed in the first months after aHSCT with an increase over 3–18 months and CD4 TC remain low for at least a year or longer, whereas CD8 + TC return sooner, i.e. 3–18 months after aHSCT." (PMID 38509633, 2024). "Hematologic malignancy patients are capable of developing a SARS-CoV-2-specific CD4 and Tfh cellular immune response after vaccination, and certain immunomodulatory therapies in the period before vaccination might increase the antigen-specific immune response." (PMID 37187728, 2023). "Additionally, malignant CD4 expression is not limited to T-cell malignancies, and can be expressed aberrantly in other hematological malignancies." (PMID 29348865, 2017). "Additionally, to our knowledge this is the only anti-CD4 CAR studied for hematologic malignancies to date." (PMID 29348865, 2017). "All but three patients were considered immunocompromised for one or more of the following reasons: uncontrolled hematological malignancy, chemotherapy, < 3 months after transplantation, prior steroid treatment, systemic immunosuppression, reduced CD4+ T-cell count, hypogammaglobulinemia." (PMID 26866481, 2016). "While evidence in some studies suggests that use of antiretrovirals in pregnancy were associated with haematological disorders in the newborns, our study also demonstrated a higher trend among infants born to mothers with CD4<200 and receiving ZDV but not among other mothers receiving triple ARVs." (PMID 25222119, 2014). "Previous research has indicated that circulating CD4+ and CD8+cells can serve as predictive or prognostic biomarkers for hematologic diseases." (PMID 41244913, 2025). "Circulating CD3+ T cells, CD4+ T cells, and CD8+ T cells have been previously reported as predictive or prognostic biomarkers in hematological diseases." (PMID 40791238, 2025).
hematological malignancies (continued). "Patients with Ttx, especially with hematologic malignancies, and here CD20 Ab-pretreated NHL in particular, failed more frequently to launch an Ab response, but typically achieved a robust CD4+-based T cell response." (PMID 41210962, 2025). "Patients with hematological malignancies have lower CD8+ T cell responses compared to those with solid tumors when infected with SARS-CoV-2, although robust CD4+ T cell responses can still be relevant in viral clearance with a predominant CD4+ immunophenotype." (PMID 40431250, 2025). "Some studies have shown that after azacitidine treatment for MDS patients, CD4+ and CD8+ T cells increased; it not only can restore the hematopoietic function but also reverse the immune derangement typical of these hematologic disorders." (PMID 40364835, 2025). "Other potential predictive factors that have been reported in patients with hematologic malignancies include age, use of BCL2 inhibitors, use of JAK2 inhibitors, absolute lymphocyte count, and circulating CD4+, CD8+, and natural killer cell counts." (PMID 37685720, 2023). "TIGIT, PD-1, TIM-3, and CD39 were more frequently expressed by γδ T cells in comparison to the corresponding CD4+ T cell population, with expression levels that were similar to that on CD8+ effector cells in both hematologic malignancies." (PMID 34820398, 2021). "In particular, we investigated the ability of MDS and AML patient-derived MSCs to induce CD4+/CD25+/FoxP3+ cells, that is, regulatory T cells (Tregs), which are known to suppress immunity also in hematological malignancies." (PMID 30359303, 2018). "HEV can evolve to chronic infection in immunosuppressed patients particularly those with solid organ transplant, hematological malignancies, and HIV positive patients with low CD4 count." (PMID 28182129, 2017). "Peripheral T lymphocytes with CD4+/CD8+ phenotype have been described in some solid and hematologic malignancies." (PMID 25143835, 2014). "The immunological profiles of CD4+ T lymphocytes (TLs) from patients with hematological malignancies differ between patients who have and have not received transfusions." (PMID 40028321, 2025). "The low incidence of hematologic diseases in pediatric populations has constrained our ability to identify significant differences in the expression levels of CD103+CD3+ T cells, CD103+CD4+ T cells, and CD103+CD8+ T cells between patients in DN/RR states and HIs, primarily due to small sample sizes." (PMID 39391310, 2024). "Expression analyses of corresponding immune effector cells derived from the BM revealed an increased expression of TIGIT, PD-1, TIM-3, and CD39 on γδ TCR cells in comparison to CD4+ cells, which was similar to that on CD8+ effector cells in both hematologic malignancies." (PMID 34820398, 2021). "Indeed, the application of a fourth mRNA vaccine dose induces not only increased titers of neutralizing antibodies, but also higher levels SARS-CoV-2-specific CD4+ and CD8+ T cell responses against the currently predominant VOC Omicron in patients with hematological malignancies." (PMID 36839516, 2023). "CD4+ cell count and HIV viral load at ICU admission, initiation of antiretroviral treatment, the presence or absence of hematological malignancies, and hepatic, renal, cardiac, neurologic, or pulmonal comorbidities had no impact on outcome in this cohort." (PMID 37243250, 2023). "Tregs, a critical subset of CD4+ T cells that are characterized by the CD4+CD25+FoxP3+ phenotype, play the role of negative immune regulation in solid tumors and hematological malignancies." (PMID 36439426, 2022).
neurological disease (58 papers, 2005 to 2025). "A series of studies have confirmed the capacity of CD4+ CTLs to directly damage neurons, oligodendrocytes, and the BBB, indicating the pathogenic roles of CD4+ CTLs in neurological diseases." (PMID 38499993, 2024). "Due to reports of CD8 + and Th1 CD4 + T cells infiltrating the brain in aging and neurological disease, we characterized transcriptional changes caused by acute local exposure to the proinflammatory cytokine IFN-γ in the ventral midbrain." (PMID 37100211, 2023). "Our results are very similar to what has previously been seen for Rift Valley Fever virus; and suggest that the CD4+T cell response is playing a role in the protection against the neurological disease associated with ZIKV." (PMID 30212537, 2018). "We noted a significant difference in weight loss and a marked difference in the signs of neurological disease between the CD4 depleted and control indicating that CD4+T cells are important for protection of the Ifnar1-/- mice from a CNS associated disease." (PMID 30212537, 2018). "Larger systematic studies of virus-associated neurologic diseases including the functional differences of CD4+ T cell subsets will further improve our knowledge of the B cell/T cell immune regulation in the CNS associated with chronic viral infections." (PMID 29709026, 2018). "In conclusion, we show that peptide epitopes of NF-L induce neurological disease and that potentially pathogenic CD4+ T cells dominate the lesions of NF-L immunized mice, a model for immune-mediated neurodegeneration." (PMID 24053384, 2013). "We found that the slow decay measured for CSF-compartmentalized variants in subjects with neurological disease was correlated with low peripheral CD4 cell count and reduced CSF pleocytosis." (PMID 19390619, 2009). "First, some risk factors for neurological disorders such as low CD4 cell count, high blood viral load, low educational attainment, tobacco use and cART regimen are not included in the NHIRD and could not be incorporated into the scoring system." (PMID 37924043, 2023). "Interestingly, in SJL/J mice, TH17 cells, which were activated in the gut, populate peripheral lymphoid organs and form a pool of pathogenic CD4+ T cells, ready to invade the central nervous system and mediate neurological disease." (PMID 24504092, 2014). "Immunosuppressive subpopulations of CD4+ T helper cells reduce autoimmune and inflammatory responses and are widely used in the treatment of neurological disorders such as GBS." (PMID 39600430, 2024). "Given the presence of CD4+ CTLs in other neurological disorders and their potential therapeutic significance, it is reasonable to investigate their role in RIBI." (PMID 38499993, 2024). "The reasons for CD4+ T-cell senescence in neurological disorders and the specific mechanisms through which senescent CD4+ T-cells promote neuroinflammation are not fully understood." (PMID 38727285, 2024). "Our observations help further understand the characteristics of CD4+ CTLs in neurological disorders." (PMID 38499993, 2024). "These genes are proven to induce the cytotoxic effects of CD4+ CTLs and have also been reported in other neurological diseases." (PMID 38499993, 2024). "Proinflammatory cytokines, including IFN-γ and TNF-α, and T cells, particularly CD4+ T cells, mediate neurological disease development and mortality in SINV-infected mice." (PMID 37243143, 2023). "As one subset of T lymphocytes, CD4+ T cells have a critical impact on the inflammation of neurological disorders." (PMID 35935951, 2022). "Our findings suggest that the IL-16/CD4 signalling pathway is closely involved in the neuroinflammation of MS and other neurological disorders through the immune and CNS resident cells." (PMID 34071825, 2021). "Here we have identified a role for CD4+T cells in protection from ZIKV-induced neurologic disease, and viral control using an established mouse model." (PMID 30212537, 2018).
neurological disease (continued). "The CD4 depleted mice showed elevated signs of neurological disease compared to the control mice beginning on day seven." (PMID 30212537, 2018). "Depletion of CD4+ or CD8+ T cells individually slightly increased the number of mice that developed neurological disease compared to vehicle-treated controls." (PMID 28340587, 2017). "This suggests that CD4+Foxp3+ Tregs elicit dual-phased roles during the progression of JEV-induced neurological disorders." (PMID 25188232, 2014). "To determine if the T cells played a pathologic role in the development of neurologic disease, we depleted mice of both CD4+ and CD8+ T cells prior to ΔNSs virus intranasal infection." (PMID 24922480, 2014). "We initially investigated the expression of Ki-67, HLA-DR and CD38 on CD4+ T cells in PBMC from healthy donors (Control), HTLV-1 infected patients who were clinically asymptomatic (HTLV), or had associated neurological disease (HAM/TSP)." (PMID 18664281, 2008). "Detection of HIV-1 RNA in CSF was more frequent in patients with neurological disease, a CD4 count lower than 200 cells/mm3 and detectable plasma HIV-1." (PMID 18096083, 2007). "Detection of HIV-1 RNA in CSF was directly related to the characteristics of the patients such as the presence of neurological disease, a CD4 count lower than 200 cells/mm3, and detectable plasma HIV-1 RNA." (PMID 18096083, 2007). "Abundance of five Th CD4+ T cell subclusters across different neurologic diseases." (PMID 39744938, 2025). "Involvement of CD4+ CTLs in animal models with neurological diseases." (PMID 38499993, 2024). "Based on this finding, we wanted to investigate whether terminally differentiated neurons expressed MHCII in vivo as this would provide insight into the mechanism by which CD4+ T cells contribute to pain and neurological diseases." (PMID 38330029, 2024). "The neurological disorder of the interaction between CD4 and BDNF has also been reported." (PMID 37786738, 2022). "More importantly, significant increases in triple and quadruple NCR expression on both CD4 and CD8 T cells from HAM/TSP subjects suggest that co-expression of multiple NCRs may be an important driver of HTLV-1 associated neurological disease." (PMID 33767694, 2021). "Because CD11c-DTR mice infected with JEV usually exhibited neurological disorder at 3–4 dpi before fully functional CD4+ and CD8+ T cell responses are induced, rapid innate cell responses such as CD11b+Ly-6Chi monocytes appear more critical to control JE progression at the early stage." (PMID 26626303, 2015). "However, neurological disorders in either L31 or L31/CD4-/- mice, with a sudden onset, seem to persist and remain stable." (PMID 24401681, 2014). "Existing evidence shows that there is a correlation between low CD4 count and the type of neurological disease, and the fact that we found men presenting with CNS diseases that had higher case fatality rates could also explain why more men were dying." (PMID 23533732, 2013). "Only 2/59 immune cell phenotypes showed significant differences in the comparison of PBMCs from healthy individuals and patients with neurological diseases: TCRαβ+CD4+CD25−CD107a+ T-cells expressed higher numbers of IL-7R molecules as compared to PBMCs obtained from control individuals." (PMID 19657390, 2009). "If we exclude individual 45 which showed a very similar profile as compared to individuals with neurological diseases, we could also identify reduced numbers of TCRαβ+CD4+CD25high+ T-cells (p = 0.0008)." (PMID 19657390, 2009). "The detection rate of RNA HIV-1 in CSF was higher in patients with neurological diseases (63.4%), in patients with a CD4+ T cell count lower than 200 cells/mm3 (64.4%), in patients not undergoing ARV therapy (82.5%), and in patients with detectable plasma HIV-1 RNA (71.4%)." (PMID 18096083, 2007).
neurological disease (continued). "To investigate the clinical relevance of CD4+cMet+ T cells observed in animal models, we examined the expression of c-Met receptor and Itgα4 by CD4+ T cells in human PBMCs of matched-age untreated patients with MS and patients with other neurological disease (OND)." (PMID 35488271, 2022). "However, a more recent report from Cheng-Mayer and coworkers group described CD4-independent, mac-tropic SHIV variants that are present in brain tissue of macaques with neurological disease." (PMID 30415390, 2019). "The association of ADC with HIV progression and depressed CD4 blood counts has been well documented, and the lack of correlation of neurological disease with the magnitude of systemic or CSF infection over the broad range of CD4 counts has also been previously noted." (PMID 16266436, 2005). "Several studies have reported that CD4 nadir and CD4 count are predictors of HIV neurological disorders in the era of modern cART." (PMID 37924043, 2023). "In the present study, we found that some genes of benefit to nervous system disease were activated (such as Lhx8, GPR88, RGS9, CD4, DRD2, RXRG, and Syt6), following the increase in the number of cholinergic and GABAergic neurons in the HSHF-diet offspring." (PMID 33819195, 2021). "As the offspring became older (16 months of age), we found that some genes of benefit to nervous system disease were activated, such as Lhx8, GPR88, RGS9, CD4, DRD2, RXRG, and Syt6, following the increase in the number of cholinergic and GABAergic neurons." (PMID 33819195, 2021). "In contrast, in disease-resistant adult animals, depletion of both CD4 T cells and CD8 T cells or depletion of B cells increased neurological disease, with higher levels of virus in the brain." (PMID 28340587, 2017). "Since CD4+ and CD8+ T cells suppressed neurological disease in adult mice, we examined these cells for activation and proliferation markers." (PMID 28340587, 2017). "It has been previously demonstrated that subjects with symptomatic WNV infections have decreased numbers of CD4+ CD25+ Foxp3+ Treg cells and mice depleted of Tregs have increased neurological disease and mortality." (PMID 26795118, 2016). "Although some of both WT and NOX2 KO mice infected with JEV exhibited neurological disorders at 5–6 dpi, a time before fully induced functional adaptive immune responses, we examined the generation of JEV-specific CD4 + and CD8 + T cell responses in surviving WT and NOX2 KO mice at 7 dpi." (PMID 38698374, 2024). "Notably, although the present study focused on CD4 T cell infiltration as a consequence of MHC II-dependent antigen presentation by microglia in AD, CD8 T cells have been shown to be expanded in neurological diseases." (PMID 39468688, 2024). "When the offspring grew older (16 months), we found that some genes of benefit against nervous system disease were activated, such as Lhx8, GPR88, RGS9, CD4, DRD2, RXRG, and Syt6, and the expression of cholinergic and GABAergic neurons biomarker protein increased." (PMID 33819195, 2021). "We therefore propose that ZIKV invasion of the CNS can occur independent of CD4+T cells however CD4+T cells are important to control viral replication and prevent the exacerbation of severe neurological disease." (PMID 30212537, 2018). "The non-depleted mice did not manifest as severe neurologic disease as the CD4 depleted mice, although we were able to detect vRNA in the brains of these mice." (PMID 30212537, 2018). "However, when both CD4+ and CD8+ cells were depleted, all treated mice developed neurological disease suggesting these cells act synergistically to suppress LACV infection." (PMID 28340587, 2017). "Diagnosis of PML-IRIS should be considered in any HIV-infected patient developing unexplained neurological disorders or worsening of a previously diagnosed PML 2 weeks to 4 months after the initiation or resumption of effective cART, independently of the CD4 cell count prior to cART." (PMID 28588577, 2017).